ALB (albumin)
Diseases named in the same sentence as ALB in open-access papers (continued):
Sharing a sentence is not in itself a finding about the gene and the disease.
Hypoalbuminemia (continued). "Given the key role that the HGF/MET axis plays in liver development and the role of the liver in albumin synthesis, hypoalbuminemia makes mechanistic sense as an expected event." (PMID 26445503, 2015). "The complications noted in infants with intestinal strictures were intestinal perforation (2/18) bacterial sepsis (2/18), severe electrolyte imbalance in (4/18), hypoalbuminemia requiring albumin transfusion (8/18) and significant cholestasis in (9/18)." (PMID 26023515, 2014). "This drug belongs to the group of cephalosporins and there are clear contraindications to its use in cases of jaundice, acidosis, or hypoalbuminemia: under these conditions the drug prevents bilirubin from binding to serum albumin." (PMID 25349754, 2014). "There is therefore a clear association between the albumin level and the severity of the insult, but it remains uncertain whether the effect of hypoalbuminemia on outcome is a cause–effect relationship or whether hypoalbuminemia is rather a marker of serious disease." (PMID 25042164, 2014). "Generally, lower albumin concentrations lead to lower osmotic pressure, so that patients with hypoalbuminemia suffer from whole body edema, ascites, and especially pericardial effusion." (PMID 25520836, 2014). "All patients had hypoalbuminemia (mean 1.4 g/dl, range 0.6 to 3 g/dL), and approximately 90% had an albumin level of less than 2.5 g/dL." (PMID 25492259, 2014). "A meta-analysis of nine prospective controlled trials on correcting hypoalbuminemia in acutely ill patients suggested that complication rates were reduced in patients who achieved serum albumin concentrations >30 g/l after albumin administration." (PMID 25042164, 2014). "The presence of hypoalbuminemia was attributed to the increased utilization of serum albumin due to acute inflammatory reactions." (PMID 24445681, 2014). "We were unable to report albumin prior to admission and thus estimate if any hypoalbuminemia was acute or chronic." (PMID 25148079, 2014). "Data from the literature show that serum albumin has a tendency to gradually decrease according to the severity of anemia, and hypoalbuminemia has been observed in mass hookworm infection." (PMID 25254370, 2014). "Hypoalbuminemia and hypocalcaemia corrected for albumin was present in 234 (90%) and 135 (52%) patients respectively." (PMID 23886009, 2013). "In light of the independent association between hypoalbuminemia and waiting list mortality, we derived and validated novel prediction models including MELD and MELDNa with the serum albumin concentration." (PMID 23349678, 2013). "Vitamin D deficiency was more prevalent in patients with hypoalbuminemia (97.4%), anemia (86.1%), HIV co-infected patients with CD4 count <200cells/mm3 (83.2%) and hypocalcemia corrected for serum albumin levels (67%)." (PMID 23886009, 2013). "Vitamin D deficiency was noted to be more prevalent in patients with hypoalbuminemia (97.4%), anemia (86.1%), HIV co-infected patients with CD4 count <200cells/mm3 (83.2%) and hypocalcemia corrected for serum albumin levels (67%)." (PMID 23886009, 2013). "Unadjusted Kaplan-Meier estimates of mortality at 3 months were 5% in patients with normal serum albumin, 13% in those with hypoalbuminemia, and 26% among hyperalbuminemic patients (P<0.0001)." (PMID 23349678, 2013). "The patients with hypoalbuminemia before therapy showed a median overall survival of 38 months compared to 40 months in patients with normal albumin levels (n = 56, HR = 2.28, p = 0,082)." (PMID 24373220, 2013). "Albumin is a lipooxygenase inhibitor in serum, which suggests that hypoalbuminemia increases synthesis of leukotrienes." (PMID 24049653, 2012). "The results suggest that mice with CIA can also develop to hypoalbuminemia, a serious complication due to accelerated metabolism of albumin in inflamed joints as demonstrated by a number of studies in RA patients." (PMID 23006786, 2012).
Hypoalbuminemia (continued). "In the situation of hypoalbuminemia, less furosemide-albumin complex can be delivered to the kidneys." (PMID 22931630, 2012). "The patient was found to have hepatomegaly and hypoalbuminemia (serum albumin concentration; 2.1–3.3 g/dL)." (PMID 23251183, 2012). "Albumin being the most abundant of all circulating proteins, hypoalbuminemia can result in a low AG." (PMID 22348860, 2012). "In particular, having a low POD1 albumin level was found to be especially predictive of adverse surgical outcomes, more so than the preoperative hypoalbuminemia." (PMID 23285146, 2012). "One patient was diagnosed as having vascular leakage on the basis of development of significant hypoalbuminaemia alone, with the plasma albumin dropping from 47 g/L to 39.5 g/L on day 4 of illness." (PMID 21886850, 2011). "As observed in 50% of MPXV infected humans diagnosed with hypoalbuminemia, significant decreases in albumin levels were also seen in this study in each of the dosage groups by day 6 post-exposure (P = 0.0056)." (PMID 20862223, 2010). "In an adult the normal range of serum albumin is defined as 3.5-5.0 g/dL and levels <3.5 g/dL is called hypoalbuminemia." (PMID 21176210, 2010). "We believe that the effectiveness of levosimendan at this low dose (0.07 μg/kg/min) was due to reduced protein binding because of hypoalbuminemia (albumin plasma level was 3.1 mg/dL in this case)." (PMID 20196861, 2010). "Residents with hypoalbuminemia had a mortality of 68.0%; dramatically higher than the rate of 12.1% among residents who had normal albumin levels." (PMID 21194423, 2010). "Serum magnesium and serum albumin level were measured to look for hypomagnesemia and hypoalbuminemia in them." (PMID 21139715, 2010). "Hypoalbuminemia (serum albumin < 3.5 g/dL) was the most common complication (50.3%), which was closely followed by ascites (48.6%) and portal hypertension (41.4%)." (PMID 19636178, 2009). "A locally derived and internally validated albumin-adjusted calcium equation differed from previously published equations and resulted in important differences in classification of calcium status in hypoalbuminemia patients." (PMID 19038049, 2008). "Classification of 343 patients with hypoalbuminemia (albumin < 33 g/L) as hypo-, normo, or hyper-calcemic using local and previously published albumin-adjusted calcium equations." (PMID 19038049, 2008). "In patients with liver cirrhosis, hypoalbuminemia is a common biochemical finding which represents a reduction in the synthetic power of cirrhotic liver to produce albumin." (PMID 19690646, 2007). "The unmeasured anion-related base deficit was greater than the total base deficit; this was predominantly due to the alkalinising effect of hypoalbuminaemia (mean albumin effect on base deficit +2.9)." (PMID 16137362, 2005). "Monitoring albumin levels postoperatively may be considered as a potential risk indicator for diagnosing HAEC in patients undergoing surgery especially TEPT, as hypoalbuminemia showed significance only within this surgical subgroup." (PMID 41505435, 2026). "Although human albumin administration improves EC function in cirrhotic patients with hypoalbuminemia, its direct effects on ECs remain unclear." (PMID 42010744, 2026). "Hypoalbuminemia was defined as a plasma albumin level below 35 g/L." (PMID 41504962, 2026). "Patients were divided into hypoalbuminemia (<3.5 g/dL) and normal albumin (3.5-6.0 g/dL) cohorts." (PMID 41975949, 2026). "Since 25(OH)D is primarily protein‐bound (mainly to DBP and albumin), hypoalbuminemia may exacerbate the bioavailability deficit, further limiting the endocrine and autocrine functions of vitamin D." (PMID 41479853, 2025). "Additionally, in patients with hypoalbuminemia, a higher mortality rate was observed (13.2%) compared to the normal albumin group (1%), and this was concluded to be an independent predictive factor for mortality." (PMID 40143356, 2025).
Hypoalbuminemia (continued). "Although point estimates varied, including a reversed but imprecise and non-significant association in patients with hypoalbuminemia (albumin ≤ 35 g/L; OR 2.06, 95% CI 0.23–25.86; P = 0.52), the overall pattern remained consistent across subgroups." (PMID 41142244, 2025). "Albumin-bound furosemide is secreted into the proximal tubule via organic anion transporters, and hypoalbuminaemia may limit this process by increasing volume of distribution and decreasing renal delivery." (PMID 41281089, 2025). "This possible dual meaning of serum albumin levels may give hypoalbuminemia a superior prognostic value for cancer outcomes, as nutritional status is an established prognostic factor in cancer." (PMID 40116494, 2025). "Clinically, serum albumin levels are widely used to assess nutritional status, with hypoalbuminemia recognized as a marker of various pathological conditions, including renal dysfunction, hepatic impairment, protein-energy malnutrition, chronic infections, and malignancies." (PMID 40757204, 2025). "Importantly, when applied to clinical samples, the method is expected to deliver reliable quantitative results even in patients with severe hypoalbuminemia (serum albumin 14.1–54.6 g/L)." (PMID 41362635, 2025). "Close to 95% of our patients had hypoalbuminemia (albumin level <35 g/L)." (PMID 39821648, 2025). "For emergency ATAAD patients with elevated TP-ALB ratios, preoperative strategies, such as albumin infusion to correct hypoalbuminemia or corticosteroid-based anti-inflammatory therapies, may potentially reduce the risk of AKI." (PMID 40421193, 2025). "A study evaluating hospitalization rates demonstrated that severe hypoalbuminemia was associated with higher rates of 30-day readmission (p = 0.005), 90-day ER visits (p = 0.006), and 90-day readmission (p = 0.001) rates compared to moderate hypoalbuminemia and normal albumin levels." (PMID 40278353, 2025). "In hypoalbuminemia patients, ALB infusion would be expected to improve outcomes." (PMID 40438354, 2025). "Elevated ACAG values are generally indicative of electrolyte imbalance, particularly in cases of hypoalbuminemia, where changes in the anion gap due to low albumin levels may affect calcium homeostasis and consequently impact bone health." (PMID 40007853, 2025). "The strong adjusted odds ratio underlines the prognostic importance of albumin, not just as a reflection of nutritional status but as a robust tool for perioperative risk modeling.The clinical relevance of hypoalbuminemia extends beyond nutritional assessment." (PMID 40698225, 2025). "In COVID-19, elevated TNF-α and IL-6 levels may suppress albumin synthesis and contribute to hypoalbuminemia." (PMID 40649865, 2025). "However, albumin infusion for the treatment of hypoalbuminemia was reported to exert adverse effects in certain patient populations." (PMID 40649163, 2025). "Second, clinical trials have revealed that in both adult and pediatric patients, exogenous albumin infusion has little benefit and might even negatively impact survival in patients with hypoalbuminemia." (PMID 40705791, 2025). "Hospitalization after outpatient investigations revealed significant hypoalbuminemia (serum albumin 19.3 g/L), proteinuria (2+), hematuria (3+), and 24 h urinary protein excretion of 1.18 g, leading to a provisional diagnosis of chronic glomerulonephritis with hypoalbuminemia." (PMID 41446863, 2025). "Advanced drug delivery systems incorporating exogenous albumin might have the potential to ameliorate the drawbacks of hypoalbuminaemia and drug-drug interactions on the pharmacokinetics of pharmaceutical agents that bind to endogenous albumin." (PMID 40656900, 2025). "For patients with hypoalbuminaemia, human albumin preparations should be administered promptly." (PMID 41305839, 2025).
Hypoalbuminemia (continued). "The same phenomenon was observed in patients who had undergone lower extremity bypass surgery; patients who had severe hypoalbuminemia (<28 g/L) before surgery had a higher readmission rate than did patients with normal albumin (within 30 days: 40.0% vs. 17.8%, within 90 days: 66.7% vs. 35.6%)." (PMID 40705791, 2025). "Elevated TP-ALB ratio may reflect hyperglobulinemia-driven inflammation and hypoalbuminemia-induced glycocalyx damage, both of which exacerbate renal dysfunction." (PMID 40421193, 2025). "Notably, there was a high concordance between serum and urinary albumin abnormalities; among patients with hypoalbuminemia, 83% (n=35) presented with concurrent elevated albuminuria, with the majority (69%; n=29) classified as severely increased." (PMID 41536368, 2025). "In the aglepristone + prostaglandin group, reduced concentration of circulating albumin (hypoalbuminemia) was observed at onset of treatment, which indicates the concomitant presence of an inflammatory and infectious process, triggering a negative influence of cytokines on hepatic synthesis." (PMID 41463815, 2025). "Severe hypoalbuminemia is albumin <25 g/L; patients categorized as ≥25 or <25 g/L." (PMID 40529137, 2025). "While hypoalbuminemia and hyperglobulinemia have individually been associated with AKI, the total protein to albumin ratio (TP-ALB ratio) integrates their combined effects, potentially serving as a stronger predictor of systemic inflammation and endothelial dysfunction." (PMID 40421193, 2025). "Furthermore, the inflammation associated with preeclampsia elevates cytokine levels, suppressing albumin production and exacerbating hypoalbuminemia." (PMID 39857389, 2025). "Although the sub-analysis by albumin level suggests that not all glomerular disease was associated with hypoalbuminemia (a consequence of significant proteinuria), a significant portion did in fact have low albumin levels." (PMID 39940317, 2025). "Given the role of albumin as a negative acute phase protein and in protein loss enteropathy, hypoalbuminemia is recognised as a predictor for severity and recurrence of CDI ​ ​." (PMID 41246573, 2025). "Albumin administration may lead to increased mortality rates in hypovolemia, hypoproteinemia, and hypoalbuminemia." (PMID 40649163, 2025). "Therefore, timely correction of hypoalbuminemia is essential for individuals with low albumin levels." (PMID 41568365, 2025). "Patients with COVID-19 were prone to hypoalbuminemia (especially albumin)." (PMID 40655399, 2025). "Using a replacement fluid that more closely matches physiological conditions may be particularly beneficial for patients with hypoalbuminemia (albumin < 4.0 g/dL) prior to TPE." (PMID 41299855, 2025). "For example, hypoalbuminemia could serve as a potential target for nutritional support or albumin supplementation strategies, warranting further investigation in interventional trials." (PMID 41343415, 2025). "We confirmed that the small, transient albumin losses described in early MCO trials did not translate into sustained hypoalbuminemia or weight loss." (PMID 41464753, 2025). "Thus, albumin is usually prescribed to temporarily manage acute hypoalbuminemia in the surgical setting." (PMID 40740823, 2025). "Additionally, in patients with hypercapnic respiratory failure, hypoalbuminemia has been identified as a significant predictor of prolonged ICU stays, where lower albumin levels are associated with increased morbidity and susceptibility to infections." (PMID 40005472, 2025). "Moreover, the level of albumin, a key hepatic synthetic protein, is an essential marker of liver function, and hypoalbuminemia is a direct consequence of hepatic dysfunction." (PMID 41428744, 2025). "In this scoping review, we aimed to identify the most used cutoff value to define hypoalbuminemia in patients with spinal metastases, and explore the association between serum albumin level and outcomes after operative and non-operative management." (PMID 40103850, 2025).
Hypoalbuminemia (continued). "For SFTS patients with coinfection, if they present with hypoalbuminemia and marked inflammatory responses, early combination therapy of corticosteroids and human albumin may be considered on the basis of targeted anti-infective treatment." (PMID 41355981, 2025). "The present research revealed that the use of albumin was linked to increased in-hospital mortality rates, and extended hospital and ICU stays compared to patients not receiving albumin, particularly among heart failure patients with hypoalbuminemia." (PMID 40279952, 2025). "Our results, which showed no outcome difference across albumin categories alone, are thus consistent with the idea that albumin as a solitary measure may be an insufficient prognostic discriminator, even if extreme hypoalbuminemia indicates illness severity." (PMID 41226896, 2025). "In patients with preoperative hypoalbuminemia, addinghuman serum albumin into the priming solution may be considered (conditionalrecommendation, low certainty)." (PMID 40630457, 2025). "Species‐specific albumin is the ideal replacement product for treating hypoalbuminemia, but canine‐specific albumin concentrate is unavailable, and therefore, in severe hypoalbuminemia, human serum albumin or synthetic colloids are administered, with their associated risks." (PMID 40521764, 2025). "A prospective randomized controlled study reports that giving albumin to critically ill patients with hypoalbuminemia may help support organ function by reducing fluid overload and enhancing tolerance to enteral nutrition." (PMID 40649163, 2025). "Hypoalbuminemia (albumin concentration < 3.5 g/dL) is common among patients with CKD and results from decreased synthesis (reduced nutrient intake, inflammatory processes, and acidosis) and increased degradation of albumin in the body (proteinuria, loss of albumin during dialysis)." (PMID 40870903, 2025). "In May 2018, the patient developed rising proteinuria with uPCR 289 mg/mmol and new hypoalbuminaemia (serum albumin 27 g/L), with relatively preserved renal function." (PMID 39979558, 2025). "The criterion for hypoalbuminemia in this study was an albumin level of <35 g/L." (PMID 41488107, 2025). "Serum albumin levels positively correlated with 25(OH)D concentrations (r = 0.51, p < 0.01), suggesting that hypoalbuminemia may co‐contribute to reduced bioavailability of vitamin D." (PMID 41479853, 2025). "Consequently, she continued to require intravenous albumin infusions every 7 to 10 days to manage persistent hypoalbuminemia and edema." (PMID 41562995, 2025). "In patients with lower ALB level before LZD therapy, prompt supplementation with human serum albumin to correct hypoalbuminemia may potentially reduce the incidence of hyponatremia." (PMID 40886330, 2025). "Cancer patients are particularly vulnerable to hypoalbuminemia, a condition precipitated by various factors such as the increased release of proinflammatory cytokines and growth factors, which suppress albumin synthesis, alongside increased vascular permeability and deteriorated nutritional status." (PMID 40051558, 2025). "Although hypoalbuminemia is generally suggestive of systemic inflammation or infection, in our study, pathogen-positive patients exhibited albumin values (~41 g/L) within or close to the normal range, whereas pathogen-negative patients had markedly reduced levels (~21 g/L)." (PMID 40943972, 2025). "Hypoalbuminemia was observed in 42 of 55 animals, suggesting issues with nutrient absorption or protein synthesis, which is consistent with previous findings on gastrointestinal disease and albumin concentrations in marmosets." (PMID 40671827, 2025). "Randomized controlled trials evaluating the impact of preoperative albumin supplementation on postoperative outcomes would be particularly valuable, as they could provide insight into whether correcting hypoalbuminemia can improve patient prognosis." (PMID 40103850, 2025).